TF (transferrin)
Diseases named in the same sentence as TF in open-access papers (continued):
Sharing a sentence is not in itself a finding about the gene and the disease.
thrombosis (25 papers, 2006 to 2025). "An increased PLR is independently associated with the risk of recurrent venous thrombosis through a mechanism involving platelet-activated TF expression and increased fibrin production." (PMID 41383227, 2025). "ICI-associated thrombosis arises from multiple mechanisms, including immune dysregulation, T cell activation, endothelial dysfunction, increased TF expression, and impaired fibrinolysis." (PMID 40429445, 2025). "Prior to the COVID-19 pandemic, increased TF expression was found to be associated with thrombosis in patients infected with other pathogenic coronaviruses and the influenza A virus." (PMID 39408067, 2024). "TF is the physiological activator of the extrinsic coagulation cascade and aberrant TF secretion into the circulation is associated with thrombosis risk in cancer patients." (PMID 38986222, 2024). "As novel assays measuring the activity of TF in plasma EVs are developing, a better comprehension of the association between TF-expressing EVs and cancer-associated thrombosis will become possible." (PMID 36013171, 2022). "Elevated levels of TF-expressing microparticles have been associated with cancer-associated thrombosis in small series 28,29." (PMID 25826750, 2015). "Overall, systemic miR-145 downregulation was associated with increased thrombus formation and TF expression, whereas treatment with miR-145 mimics effectively diminished both, highlighting the strong potential of miR-145-based therapies for managing venous thrombosis in humans." (PMID 40299499, 2025). "Supporting the translational relevance of these findings, venous thrombosis patients exhibited lower miR-145 levels and higher TF expression, mirroring the results observed in animal models." (PMID 40299499, 2025). "Coincidentally, a recent study demonstrated that endothelium-specific SIRT6 deletion promotes arterial thrombosis in mice by enhancing TF expression and activating pro-inflammatory signaling." (PMID 38186648, 2023). "Recently, a study revealed that targeted deletion of SIRT6 in the endothelium of mice promotes arterial thrombosis by increasing TF expression and activating pro-inflammatory signaling, highlighting the importance of SIRT6 in regulating thrombotic processes." (PMID 38186648, 2023). "The role of transferrin in promoting hypercoagulability was further investigated in a mouse thrombosis model induced by FeCl3." (PMID 31811276, 2020). "Elevated levels of monocyte-derived TF+ MVs observed in hyperlipidemia patients are suggested to contribute to arterial thrombosis after rupture of atherosclerotic plaques." (PMID 26925191, 2016). "In arterial thrombosis, mainly located on atheroma, inflammation promotes plaque rupture and increases TF expression in endothelial cells and monocytes." (PMID 16630353, 2006). "Consequently, the relative ratio of TF and TF pathway inhibitor expression in MoMVs tilts the scales of their activity towards either thrombosis or hemorrhage." (PMID 35740926, 2022). "Following TF-activated coagulation cascade, the nature of formed intravascular thrombus (e.g., deep vein thrombosis [DVT] and “DIC”) has been presumed to be the same nature to the hemostatic plug (e.g., blood clots after an injury)." (PMID 30127669, 2018). "SIRT6 knockdown increases TF expression and initiates pro-inflammatory pathways, protecting endothelium SIRT6 from experimental arterial thrombosis." (PMID 41567643, 2025). "However, sub-chronic stress did not modify the expression of Sirt1, a modulator of TF expression and of arterial thrombosis, as previously shown in BDNFMet/Met mice, in all experimental groups considered." (PMID 30347685, 2018).
malaria (24 papers, 2008 to 2025). Malaria is a serious and sometimes fatal disease caused by a parasite that commonly infects a certain type of mosquito which feeds on humans. "More recent reports of associations between other markers of iron stores (transferrin saturation, soluble transferrin receptor [sTFR]/log10 ferritin ratios) and malaria in pregnant women and children support the notion of a true biological effect." (PMID 35619134, 2022). "Decreased ferritin and transferrin saturation are associated with protection against malaria in African children." (PMID 30219845, 2019). "Low transferrin saturation (<10%) was similarly associated with lower malaria risk (IRR, 0.8; 95% CI, 0.6, 0.9; P = .016)." (PMID 30219845, 2019). "Malaria induced haemolysis causes free non-transferrin-bound iron and free haemoglobin to be released which can cause oxidative stress and adding supplemental iron to this milieu may not improve erythroblastic iron supply." (PMID 18461143, 2008). "Because addition of P. falciparum-infected plasma to EC or cytoadherance is associated with TF expression, ROS production, apoptosis, and activation of NF-κB, it is plausible that therapeutic targeting of O2− would be effective to prevent the endothelial activation observed in severe malaria." (PMID 24586264, 2014). "Malaria was found in 375 out of 432 (87%), and ID in 1.8% according to diagnosis by adjusted ferritin only and in 12.9% according to transferrin saturation." (PMID 33801005, 2021). "Its primary function is the import of iron bound to transferrin but several other ligands including ferritin, arenaviruses or malaria parasite use CD71 to enter cells." (PMID 33110194, 2020). "Arenaviruses and the malaria parasite exploit CD71 for cell invasion and epitopes on CD71 for interaction with transferrin and pathogenic hosts were identified." (PMID 30850661, 2019). "During the acute malaria attack (day 0), hepcidin levels were raised, which was reflected in low levels of Fe, transferrin and transferrin saturation." (PMID 30537973, 2018). "The delivery of extracellular iron from TF to infected erythrocytes is the source of ferric ions for malaria parasites." (PMID 25656928, 2015). "In humans, there is a correlation between transferrin saturation and ALT levels in patients with symptomatic malaria, suggesting that iron status may be linked to malaria-induced liver pathology in humans." (PMID 37812650, 2023). "Furthermore, studies have found that iron bound to transferrin is the source of ferric ions for malaria parasites within mature erythrocytes." (PMID 33517144, 2021). "The prevalence of ID is underestimated in African children when defined using the WHO guidelines, especially in malaria-endemic populations, and the use of transferrin saturation may provide a more accurate approach." (PMID 32102669, 2020). "The alteration of TF level may influence the balance between inhibiting and promoting the survival of malaria parasite." (PMID 25656928, 2015). "However, this adaptive response could have detrimental consequences in the context of malaria; by increasing the pool of bioavailable iron, particularly in the form of transferrin-bound iron, the host may inadvertently facilitate greater access to iron by the parasite." (PMID 40871363, 2025). "ELISA-based testing of human IgG antibody levels against the peptides revealed that the transferrin-derived peptides, TRANS-P1, TRANS-P2 and a salivary peroxidase peptide (PEROX-P3) were able to distinguish between malaria-infected and uninfected groups." (PMID 31973044, 2020). "These compounds may have a less unfavourable effect on malaria, as they do not produce toxic non-transferrin bound iron (NTBI)." (PMID 28129772, 2017). "The possible unfavourable impact of iron supplementation on malaria might be less when slow-release iron compounds are used instead of ferrous salts, because no toxic non-transferrin bound iron is formed." (PMID 28129772, 2017).
colon carcinoma (23 papers, 1996 to 2025). "And TF-linked liposomes encapsulated with oxaliplatin can be used for targeted delivery of chemotherapeutic drugs in colon cancers with high TfR1 expression to improve anti-tumor efficacy." (PMID 36910614, 2023). "Elevated body iron stores have been proposed to correlate with an increased risk of colon cancer and an increased proportion of transferrin loaded with iron has been linked with an increased cancer incidence, particularly in individuals who have a high intake of iron." (PMID 16755300, 2006). "Other studies have shown that miR-19a is negatively correlated with TF expression in patients with early colon cancer, and can inhibit TF expression in vitro and inhibit the migration and invasion of CRC." (PMID 33865381, 2021). "Furthermore, miR-19a can reduce TF expression in colon cancer cells, and inhibiting TF through miR-19a reduces migration and invasion of colon cancer cells mediated by TF." (PMID 37280670, 2023). "Unused plasmids in other organs will be progressively destroyed by cytoplasmic nucleases, and the nanoparticles will be cleared because PEG and PEI are biodegradable, thus avoiding any toxicity problem, It has been shown that Transferrin (Tf)-receptors are highly expressed in colon tumors." (PMID 35982950, 2022). "Therefore in the present work we evaluated an effect of transferrin—a necessary ferroptotic factor on IL-6 synthesis and release by colon cancer cells." (PMID 34681200, 2021). "Addition of transferrin to the surface of PEGylated oxaliplatin-loaded liposomes increased tumor accumulation over free oxaliplatin or untargeted liposomes leading to the highest tumor growth inhibition against C26 colon carcinoma-bearing mice." (PMID 23533772, 2013). "Thus, the ITTC accumulation in HT29 human colon tumors was improved after its covalent conjugation to transferrin in place of albumin, presumably because of the transferrin interactions with the cancer cell surface receptors." (PMID 20497549, 2010). "PEGylated liposomes functionalized with transferrin (TF-PEG liposomes) with sodium borocaptate (BSH) with concentrations of 107–123 nm/26–30 μg/μmol of lipid 6–8% were verified for the specificity of the TF-receptor mediated binding in vitro in colon carcinoma cells." (PMID 37175627, 2023). "Patients with colon cancer liver metastases who have undergone partial hepatectomy have a poor prognosis if their serum TF levels are less than 190 mg/dL, which means serum transferrin level is a potential predictor of poor OS in patients with CRC liver metastases after hepatic resection." (PMID 36910614, 2023). "MiR-545, which is highly expressed in colon cancer cell lines (HT-29, LoVo, and HCT-116), inhibits ferroptosis by inhibiting TF expression, lowering intracellular iron accumulation, as well as reducing lipid peroxidation." (PMID 36910614, 2023). "Previous work from our laboratory have extensively used Transferrin and Insulin (jointly termed here as GF or growth factors) in combination to activate IGF-1R-mediated cell survival signaling in colon cancer cells." (PMID 24083380, 2013). "Using the cutoff value of 0.397 derived from the training set, exosomal TF-Ag-α achieved 100% sensitivity, specificity, AUC, PPV, NPV, and ACC in distinguishing colon cancer patients (stages I–IV) from controls, surpassing the performance metrics observed in the training cohort." (PMID 41374931, 2025). "The specificity of the TF-receptor mediated binding was verified in vitro in colon carcinoma cells, while an ex vivo biodistribution study, conducted on colon carcinoma-bearing mice, revealed, by MIP-MS, prolonged residence of TF-PEG liposomes in the circulation." (PMID 36552793, 2022). "It is not clear why the transferrin concentration is increased in the serum of colon cancer patients as the predicted response to inflammation is a decrease for this protein." (PMID 16755300, 2006).
colon carcinoma (continued). "Additionally, the expressions of SPARCL1, CP and TF differed significantly between stage IV colon cancer and normal (p < 0.05), while that of SPARCL1, CDH2, CP and SERPINA5 differed significantly between rectum adenocarcinoma and normal tissues." (PMID 34422629, 2021).
Insulin resistance (23 papers, 2012 to 2026). Increased resistance towards insulin, that is, diminished effectiveness of insulin in reducing blood glucose levels. "These two studies suggest that functional iron deficiency, indicated by low serum iron and low transferrin saturation, is linked to impaired glucose metabolism and a higher risk of insulin resistance in children." (PMID 40218969, 2025). "Our results also do not replicate those of a prospective study where serum transferrin was inversely associated with insulin resistance and baseline serum ferritin, transferrin, and total serum iron were significantly associated with incident T2DM." (PMID 38715055, 2024). "A prospective study assessing several biomarkers of iron metabolism and insulin resistance demonstrated that serum transferrin had a statistically significant inverse association with insulin resistance." (PMID 35538408, 2022). "Hepcidin in turn activates transferrin, resulting in iron overload, causing insulin resistance and impaired glucose tolerance." (PMID 35747025, 2022). "Transferrin has been associated with insulin resistance, through increasing the rate of adipocyte lipolysis and circulating free fatty acid." (PMID 22815867, 2012). "DIOS is characterized by hyperferritinaemia, metabolic syndrome, insulin resistance, high serum ferritin (SF), and high transferrin saturation, but normal serum iron levels." (PMID 41596552, 2026). "In another study of 509 individuals with a 7 year follow up period, ferritin and transferrin were prospectively positively associated with insulin resistance (as estimated by HOMA2-IR), adipocyte and hepatic insulin resistance and development of T2DM." (PMID 37029208, 2023). "Our previous study confirmed that FoxO6-mediated IL-1β is involved in hepatic inflammation and insulin resistance via TF/PAR2/Akt pathway in aging and diabetic liver." (PMID 34631216, 2021). "The issue of transferrin and its binding capacity implication on insulin resistance is much more controversial than that of ferritin, and our results suggest a complex metabolic dysregulation." (PMID 32821534, 2020). "According to Vincent, iron overload (haemochromatosis) may prevent chromium uptake by transferrin (Tf), thus leading to insulin resistance and diabetes." (PMID 29164513, 2018). "Six proteins function in regulating glucose homeostasis, insulin resistance, and β-cell function, including SHBG, FETUB, PRG4, GSN, CFD, and TF, among which SHBG and FETUB are markers of insulin sensitivity and the expression of TF in adipose tissue is positively associated with insulin sensitivity." (PMID 38182717, 2024). "In a study on women with polycystic ovary syndrome, it has been demonstrated that insulin resistance decreases the concentration of transferrin in circulation, but does not affect the remaining parameters of iron metabolism." (PMID 40218969, 2025).
liver fibrosis (23 papers, 2013 to 2025). "Studies showed that mice with liver-specific TF deficiency and high iron diets are prone to liver fibrosis caused by ferroptosis." (PMID 40938883, 2025). "In line with this idea, we observed that 10 of the 16 LoF mutation patients in whom liver fibrosis had been reported also had high transferrin saturation levels (≥ 60% in men and ≥ 50% in women), pointing that three transferrin saturation values were missing in the 16 considered patients." (PMID 40225168, 2023). "Notably, altering iron metabolism in hepatocytes using hepatocyte-specific deletion of the transferrin (Trf) gene not only increases susceptibility to ferroptosis but also to liver fibrosis." (PMID 35963845, 2022). "Interestingly, in contrast to the previous findings of TF having a positive role in ferroptosis, a recent study showed that hepatocyte-specific TF knockout mice have higher susceptibility to ferroptosis in liver fibrosis." (PMID 33499222, 2021). "However, hepatocyte-specific TF knockout mice are more susceptible to high-iron diet-induced ferroptotic liver fibrosis, indicating that hepatic TF plays a protective role in ferroptosis-induced liver fibrosis." (PMID 33117818, 2020). "In this study we noted that advanced liver fibrosis is present in a high percentage of patients, and it is independently associated with ferritin and transferrin levels, indicating that these can be predictive markers for a group of hard-to-treat patients with HCV infection." (PMID 24348638, 2013). "SLC39A14 transferred non-transferrin-bound iron into the mouse liver resulting in ferroptosis to promote liver fibrosis." (PMID 38602575, 2024). "PAR1, as the main thrombin receptor, is closely related to TF expression and plays a key role in liver fibrosis (Gutiérrez-Rodríguez and Herranz, 2015; Flaumenhaft and De Ceunynck, 2017)." (PMID 37693903, 2023). "Given excess iron deposits in the liver, cells take up transferrin-dependent iron through TFR, and store it in the cytoplasm as Ft, causing hepatocyte damage and the development of liver fibrosis." (PMID 35698613, 2022). "Spearman’s correlation showed a moderate correlation between the serum transferrin levels and hepatic mRNA expression in individuals with advanced liver fibrosis and available matched serum-mRNA sample pairs (cohort i)." (PMID 33593348, 2021). "The administration of mannose improves the clinical and biochemical outcome (including serum transferrin isoforms); however, patients can still develop progressive liver fibrosis." (PMID 34291020, 2021). "Moreover, 20–35% of CHC patients show increased levels of transferrin saturation (TS), serum iron (Fe), and ferritin (Ft), and these parameters correlate significantly with liver fibrosis." (PMID 41157574, 2025). "Transferrin-KO mice developed liver fibrosis after a high iron diet." (PMID 40149659, 2025). "This study revealed that serum iron markers (especially ferritin and transferrin) might be used as surrogate markers for both liver fibrosis and necroinflammatory activity.Patients with chronic hepatitis C (CHC) often have elevated serum iron markers, which may worsen liver injury." (PMID 24348638, 2013). "Liver transferrin (TRF), a serum-abundant metal-binding protein, has been shown to alleviate liver fibrosis via ferroptosis." (PMID 34970553, 2021).